PLAGL2 (PLAG1 like zinc finger 2)
Diseases named in the same sentence as PLAGL2 in open-access papers (continued):
Sharing a sentence is not in itself a finding about the gene and the disease.
prostate carcinoma (7 papers, 2016 to 2023). A carcinoma that arises from epithelial cells of the prostate gland. "Overall, these findings demonstrated that GATA5 inhibits prostate cancer progression by regulating PLAGL2." (PMID 35565203, 2022). "Furthermore, the mechanism by which GATA5 inhibits prostate cancer progression through regulating PLAGL2 via the FAK/PI3K/AKT pathway was also explored." (PMID 35565203, 2022). "In addition, they found that the extent of PLAGL2 expression in prostate cancer is closely related to the prognoses of patients." (PMID 29662235, 2018). "The precise role of PLAGL2 in prostate cancer (PCa) is still unknown." (PMID 27537362, 2016). "EPSTI1 for breast cancer, AR for prostate cancer, GRAP for oral squamous cell carcinoma, CDCP1 and PLAGL2 for ovarian cancer were the only five direct targets identified for miR‐654‐5p thus far." (PMID 33135351, 2020). "In addition, we confirmed that GATA5 inhibited prostate cancer progression, including EMT, by regulating PLAGL2 via the FAK/PI3K/AKT pathway." (PMID 35565203, 2022).
colon cancer (6 papers, 2016 to 2023). "To further explore the function of PLAGL2 in colon cancer cells, we first transfected sh-PLAGL2 into SW480 and HCT116 cells to establish stable knockdown cell lines with the lentiviral vector." (PMID 32413870, 2020). "The chromosome location of PLAGL2 was a high recurrence-focal locus for gene amplification in the colon cancer." (PMID 27537362, 2016). "In addition, based on our in silico analysis, LncPVT1, CircPVT1/miR-484, miR-24-3p, miR-423-5p/PLAGL2 axis might be involved in colon cancer development." (PMID 37573419, 2023).
bladder cancer (5 papers, 2018 to 2026). "Our study found that the risk of lymph node metastasis in PLAGL2-positive bladder cancer patients was 1.661 times higher than that of PLAGL2-negative bladder cancer patients." (PMID 29662235, 2018). "RACGAP1-mediated activation of RhoA can enhance the activity of YAP1/TAZ, thereby assisting PLAGL2 in promoting the progression of bladder cancer." (PMID 38898473, 2024). "In our study, the positive rate of PLAGL2 expression in the bladder cancer tissue was 83.3%; of which weak positive rate (+) was 20.2%, intermediate positive rate (++) was 36.0%, and strong positive rate (+++) was 27.1%." (PMID 29662235, 2018). "We analyzed the relationship between the expression of PLAGL2 and the clinicopathological features and the prognoses of bladder cancer." (PMID 29662235, 2018). "Moreover, Pleomorphic adenoma gene like-2 (PLAGL2) facilitated bladder cancer progression via RACGAP1/RhoA GTPase/YAP1 signaling, and its proproliferative and prometastatic effects were negated by the RhoA inhibitor simvastatin." (PMID 39101139, 2024). "PLAGL2 is upregulated in various tumors, including bladder cancer (BCa)." (PMID 37454211, 2023). "Although the expression and carcinogenic mechanisms of PLAGL2 have been extensively studied, the role of PLAGL2 in the development and progression of bladder cancer is unknown." (PMID 29662235, 2018). "Furthermore, PLAGL2 could be used as a predictor for recurrence-free and overall 5-year survival of bladder cancer patients." (PMID 29662235, 2018). "Therefore, we decided to study the expression of PLAGL2 in bladder cancer." (PMID 29662235, 2018).
breast carcinoma (5 papers, 2020 to 2023). "It was also reported that PLAGL2 was associated with chemotherapeutic drug resistance of adriamycin in breast cancer by activating Wnt pathway as well." (PMID 36879254, 2023). "In breast cancer, miR-22-3p exhibited a tumor-suppressive function by targeting the expression of PLAGL2." (PMID 37620594, 2023).
leukemia (5 papers, 2018 to 2021). A malignant (clonal) hematologic disorder, involving hematopoietic stem cells and characterized by the presence of primitive or atypical myeloid or lymphoid cells in the bone marrow and the blood. "Plag1 and its homologue, Plagl2, have also previously been implicated in leukemia, being observed as candidate cooperating oncogenes in a retroviral insertion screen with the CBFβ-MYH11 product of the inv16 gene rearrangement." (PMID 30890554, 2019). "Finally, proto-oncogene pleomorphic adenoma gene-like 2 (PLAGL2) has been implicated in a variety of cancers, including leukemia, gastrointestinal, colon, lung, and prostate." (PMID 31749682, 2019).
bladder urothelial carcinoma (4 papers, 2018 to 2022). "PLAGL2 has aberrant expression in bladder urothelial carcinoma, and is closely associated with clinical characteristics of the patients, such as tumor number, stage, and metastasis." (PMID 35565203, 2022). "The purpose of this study was to investigate PLAGL2 expression associated with pathological features and prognosis and predicted lymph node metastases in the bladder urothelial carcinoma (BUC) tissue." (PMID 29662235, 2018).
colorectal adenocarcinoma (4 papers, 2017 to 2023). The most common type of colorectal carcinoma. "According to existing literature, PLAGL2 has been reported to activate WNT pathway in colorectal adenocarcinoma." (PMID 31911754, 2020). "In addition, PLAGL2 may be a very upstream key molecule regulating epithelial-mesenchymal transition and participated in Wnt/β-catenin signaling in colorectal adenocarcinoma." (PMID 36873735, 2023).
ependymoma (4 papers, 2023 to 2025). A WHO grade II, slow growing tumor of children and young adults, usually located intraventricularly. "Neuroepithelial tumors with fusion of PLAGL1 or amplification of PLAGL1/PLAGL2 have recently been described often with ependymoma-like or embryonal histology respectively." (PMID 39228008, 2024).
lung cancer (4 papers, 2010 to 2023). A malignant neoplasm involving the lung. "For instance, PLAGL2 overexpression is associated with lung cancer progression, where advanced stages of lung cancer are associated with a higher PLAGL2 expression." (PMID 34586726, 2021). "Overexpression of PLAGL2 has been implicated in lung cancer." (PMID 36873735, 2023).
neuroblastoma (4 papers, 2020 to 2022). Neuroblastoma (NB) is the most common solid, extracranial childhood tumor. "Here we demonstrate for the first time that PLAGL2 directly regulates the transcription of MYCN, the well-known key regulator of neuroblastoma cell differentiation, disclosing a previously unknown mechanism underlying the differentiation-regulating function of PLAGL2." (PMID 32087738, 2020). "High PLAGL2 messenger RNA expression in neuroblastoma patient tumors also correlated to poor overall survival." (PMID 35763016, 2022). "PLAGL2 was recently described as a regulator of MYCN expression in peripheral neuroblastoma, with knockdown of PLAGL2 inducing neurite outgrowth and differentiation in neuroblastoma cells." (PMID 35763016, 2022). "We examined the function of PLAGL2 in regulating neuroblastoma cell fate by cell viability assay, colony formation and Western blotting of differentiation markers." (PMID 32087738, 2020). "For example, miR-214 was found to target the 3’UTR of PLAGL2 mRNA and down-regulated PLAGL2 expression in neuroblastoma cells." (PMID 32087738, 2020). "We discovered that PLAGL2 expression is regulated by MYCN at the transcription level in neuroblastoma cells." (PMID 32087738, 2020). "Together these findings strongly support that PLAGL2 plays a critical role in maintaining the proliferative and undifferentiated status of cells of neuronal origin, including neuroblastoma cells." (PMID 32087738, 2020). "miR-506-3p is a potent differentiation inducer and a strong repressor of MYCN expression in neuroblastoma cells by targeting PLAGL2 transcription factor." (PMID 33614505, 2020). "This is consistent with our findings showing that knocking down PLAGL2 expression induced neuroblastoma cell differentiation and inhibited cell proliferation." (PMID 32087738, 2020). "Here we investigated the cellular responses to the aberrant PLAGL2 expression in neuroblastoma cells." (PMID 32087738, 2020). "Here we identified for the first time PLAGL2 as a direct target of miR-506-3p in neuroblastoma cells, expanding the miRNA regulatome of PLAGL2 expression." (PMID 32087738, 2020). "As a key regulator of neurblastoma cell fate, whether PLAGL2 transcription is regulated by other TFs, especially TFs that are relevant in neuroblastoma tumorigenesis, is certainly a key question that needs to be addressed." (PMID 32087738, 2020). "Here we investigated the transcriptional regulation of PLAGL2 by N-Myc in neuroblastoma cells." (PMID 32087738, 2020). "In addition, the mechanisms of action of PLAGL2, as a new key player in regulating neuroblastoma cell fate, warrant further investigation." (PMID 32087738, 2020). "We next investigated whether N-Myc regulate endogenous expression of PLAGL2 in a panel of neuroblastoma cell lines." (PMID 32087738, 2020). "Moreover, we found that PLAGL2 knockdown induced neuroblastoma cell differentiation and reduced cell proliferation, and combined knockdown of PLAGL2 and MYCN showed a synergistic effect." (PMID 32087738, 2020). "Given the complexity of the PLAGL2 transcriptome indicated in the published studies, it is reasonable to speculate that MYCN is not the sole transcription target that mediates the function of PLAGL2 in neuroblastoma cells." (PMID 32087738, 2020). "PLAGL2 is hypothesized to maintain neuroblastoma tumor cells in an undifferentiated state." (PMID 35763016, 2022). "Overall, the molecular mechanisms that regulate PLAGL2 expression and function have been demonstrated to be complex, and future effort is certainly needed to fully dissect the molecular network involved in modulating PLAGL2 expression and functions in neuroblastoma." (PMID 32087738, 2020). "We further confirmed the reciprocal regulation between endogenous PLAGL2 and MYCN in multiple neuroblastoma cell lines." (PMID 32087738, 2020).
neuroblastoma (continued). "We investigated the clinical relevance of PLAGL2 expression by examining the correlation of tumor PLAGL2 mRNA levels with MYCN mRNA expression and patient survival using public neuroblastoma patient datasets." (PMID 32087738, 2020). "More strikingly, we found that high tumor PLAGL2 mRNA levels were significantly correlated with high MYCN mRNA levels and poor patient survival in neuroblastoma patients." (PMID 32087738, 2020). "Our findings altogether suggest that the interplay network formed by PLAGL2, MYCN and miR-506-3p is an important mechanism in regulating neuroblastoma cell fate, determining neuroblastoma prognosis, and mediating the therapeutic function of retinoic acid." (PMID 32087738, 2020). "In neuroblastoma, PLAGL2 induces cell cycle regulation and apoptosis by activating the Nip3 promoter independent of HIF‐1;11 however, the mechanism underlying PLAGL2‐mediated apoptosis regulation in HCC is not yet fully understood." (PMID 34586726, 2021). "Whether these non-TF functions of PLAGL2 play a role in modulating neuroblastoma cell fate certainly warrants future investigation." (PMID 32087738, 2020). "To evaluate the clinical relevance of PLAGL2 in neuroblastoma patients, we examined the correlation of PLAGL2 mRNA expression with MYCN mRNA levels in neuroblastoma patients as well as its correlation with patient survival based on published neuroblastoma patient datasets." (PMID 32087738, 2020). "The cellular functions of PLAGL2 in neuroblastoma cells have not been fully defined previously." (PMID 32087738, 2020). "Moreover, N-MYC regulates PLAGL2 transcription through five N-MYC-binding E-boxes in the PLAGL2 promoter region, forming a positively regulatory loop between the two transcription factors, which is crucial for expression of each other in neuroblastoma tumors." (PMID 33614505, 2020). "Significant positive correlation between PLAGL2 and MYCN mRNA levels were observed in all three datasets, suggesting that the positive regulatory loop formed between PLAGL2 and MYCN play a critical role in controlling the expression of each other in neuroblastoma tumors." (PMID 32087738, 2020).
embryonal tumor (3 papers, 2022 to 2023). "This study characterized histopathologically and radiologically two additional cases of the novel embryonal tumor characterized by PLAGL2 gene amplification." (PMID 37349135, 2023). "PHOX2B expression focally exceeding 20%–30% of cells can be observed in ETMR, and focal PHOX2B expression in a subset of tumor cells was observed in a single case of CNS embryonal tumor NEC (HGNET with PLAGL2 amplification)." (PMID 35763016, 2022). "Among CNS embryonal tumors, focal immunoreactivity for PHOX2B was observed in most (5/7) embryonal tumors with multilayered rosettes (ETMR) and a single high‐grade neuroepithelial tumor (HGNET) with PLAGL2 amplification; the remaining 27 CNS tumors were essentially immunonegative (<0.05% positive)." (PMID 35763016, 2022).
benign prostatic hyperplasia (2 papers, 2016 to 2018). A non-cancerous nodular enlargement of the prostate gland. "Immunohistochemistry analysis showed that staining of PLAGL2 in PCa tissues was significantly higher than that in benign prostatic hyperplasia (BPH) tissues." (PMID 27537362, 2016).
brain tumor (2 papers, 2023 to 2025). "Our findings further support that in a brain tumor context, both PLAGL1 and PLAGL2 likely act as oncogenes, whose amplification and resultant overexpression drive tumor development." (PMID 36437415, 2023). "While PLAG1 and PLAGL2 have been described as proto-oncogenes, PLAGL1 seems to act in a context dependent manner either as a tumor suppressor gene or, as recently described by us and others, as a proto-oncogene in the brain tumor context." (PMID 40751809, 2025).
CNS embryonal tumor (2 papers, 2022 to 2025). "In our study, PHOX2B positivity was also noted in a single unusual case of CNS embryonal tumor NEC (a HGNET with PLAGL2 amplification)." (PMID 35763016, 2022).
lymph node metastasis (2 papers, 2016 to 2018). "Logistic regression analysis showed that PLAGL2 expression was an independent risk factor for BUC lymph node metastasis (P < 0.05)." (PMID 29662235, 2018). "Multivariate logistic regression analysis suggested that PLAGL2 overexpression was an independent risk factor for lymph node metastasis of BUC (P < 0.05)." (PMID 29662235, 2018). "COX multivariate analysis suggested that lymph node metastasis and overexpression of PLAGL2 are important factors for diminishing the 5-years postoperative RFS and OS of the BUC patients." (PMID 29662235, 2018). "COX singular factor regression analysis showed that tumor size, tumor cT, lymph node metastasis, and the level of PLAGL2 expression were correlated to 5-year RFS of BUC (P < 0.05)." (PMID 29662235, 2018). "COX multivariate analysis showed that a high cT stage, lymph node metastasis, and overexpression of PLAGL2 were predictors of a shorter 5-year survival time (P < 0.05)." (PMID 29662235, 2018). "COX single factor regression analysis showed that tumor size, cT, lymph node metastasis, and overexpression of PLAGL2 were correlated with disease-free OS of BUC (P < 0.05)." (PMID 29662235, 2018). "COX multivariate analysis suggested that lymph node metastasis and PLAGL2 overexpression resulted in a shorter RFS for BUC patients (P < 0.05)." (PMID 29662235, 2018). "The relationships of PLAGL2 expression with lymph node metastasis and patient survival have great clinical significance." (PMID 29662235, 2018). "Overexpression of PLAGL2 can be an independent predictor for lymph node metastasis and patient survival." (PMID 29662235, 2018). "Thus PLAGL2 overexpression can be an independent predictor for lymph node metastasis." (PMID 29662235, 2018). "Based on subgroup analysis of lymph node metastasis, we found that the pelvic lymph node metastasis of BUC was significantly correlated with tumor size, multiplicity of tumors, tumor grade, tumor cT, and the level of PLAGL2 expression." (PMID 29662235, 2018).
multiple myeloma (2 papers, 2022 to 2023). "HCP5/miR-128-3p/PLAGL2 signaling was associated with an increased risk of multiple myeloma through altered Wnt/-catenin/cyclin D1 signaling." (PMID 36793341, 2022).
ovarian carcinoma (2 papers, 2020 to 2023). A malignant neoplasm originating from the surface ovarian epithelium. "It had been shown that overexpression of PLAGL2 was involved in the process of carcinogenicity of ovarian cancer cells through modulation of lncRNA ARAP1-AS1/miR-4735-3p/PLAGL2 axis." (PMID 36879254, 2023).
rectal cancer (2 papers, 2017 to 2023). A primary or metastatic malignant neoplasm that affects the rectum. "The results showed that E2F4 and SP3 correlated significantly with POFUT1 and PLAGL2 in colon and rectal cancer, which indicated E2F4 and SP3 are the most likely transcription factor binding to this bidirectional promoter and causing co-expression of the gene pair." (PMID 29108255, 2017). "Future articles in this series will go into more details about the effects of hub genes of PLAGL2, ZNF337 and ALG10 on the phenotype of rectal cancer cells after irradiation in vitro and in vivo." (PMID 36879254, 2023). "Furthermore these microRNAs can directlay target PLAGL2 and POFUT1 and repress the expression of both genes in colon and rectal cancer." (PMID 29108255, 2017).
breast neoplasm (1 paper, 2020). A benign or malignant neoplasm of the breast parenchyma. "MiR-449a inhibits cell migration and invasion in Breast Neoplasms by targeting PLAGL2." (PMID 33193744, 2020).
bronchopulmonary dysplasia (1 paper, 2024). Bronchopulmonary dysplasia is a chronic respiratory disease that results from complications related to lung injury during the treatment of infant acute respiratory distress syndrome in low-birth-weight premature infants or from abnormal lung development in older infants. "To investigate the impact of PLAGL2 on bronchopulmonary dysplasia (BPD), we established an AECII cell line with upregulated PLAGL2 expression." (PMID 39102510, 2024).
cataract (1 paper, 2025). Partial or complete opacity of the crystalline lens of one or both eyes that decreases visual acuity and eventually results in blindness. "A DT model trained on the in vivo dataset (GSE230320), using the genes PLAGL2, CMTM7, NR1D2, and PCYT1B, not only accurately predicted cataracts in the other in vivo dataset but also demonstrated good predictive performance in two separate ex vivo datasets." (PMID 40027191, 2025). "NR1D2 and PLAGL2 had a minor negative influence on predicting “no cataracts”." (PMID 40027191, 2025).
diabetic retinopathy (1 paper, 2025). "A paralog of PLAGL2, the PLAG1 gene, has recently been implicated in diabetic retinopathy." (PMID 40027191, 2025).
endometrial cancer (1 paper, 2023). Primary or metastatic malignant neoplasm involving the endometrium (mucous membrane that lines the endometrial cavity). "High expression of PLAGL2 enriched in signaling pathways such as endocytosis, endometrial cancer and others." (PMID 36879254, 2023).
hepatoblastoma (1 paper, 2023). Hepatoblastoma (HB) is a malignant hepatic tumor and is the most common pediatric liver cancer. "PLAG1 was first isolated from salivary gland adenomas, while PLAGL2 was isolated in hepatoblastomas." (PMID 37371750, 2023). "The finding that PLAG1 is overexpressed and induces IGF2-p3 activation also in hepatoblastoma cell lines suggests that PLAG1 and PLAGL2 may play a wider role in IGF2 overexpression in cancer." (PMID 37371750, 2023).
Hirschsprung disease (1 paper, 2020). Hirschsprung disease (HSCR) is a congenital intestinal motility disorder that is characterized by signs of intestinal obstruction due to the presence of an aganglionic segment of variable extent in the terminal part of the colon. "We previously demonstrated that the pleomorphic adenoma gene like-2 (PLAGL2) is involved in the pathogenesis of Hirschsprung disease." (PMID 31827238, 2020).